PGAP3 (post-GPI attachment to proteins phospholipase 3)
Description:
Involved in the fatty acid remodeling steps of GPI-anchor maturation where the unsaturated acyl chain at sn-2 of inositol phosphate is replaced by a saturated stearoyl chain. May catalyze the first step of the fatty acid remodeling, by removing the unsaturated acyl chain at sn-2 of inositol phosphate, generating a lyso-GPI intermediate (Probable). The fatty acid remodeling steps is critical for the integration of GPI-APs into lipid rafts (By similarity).
Synonyms: hCOS16; CAB2; PERLD1; MGC9753; PP1498; PER1; AGLA546
Tractability: Antibody: UniProt predicts a signal peptide or a membrane-spanning region; the Human Protein Atlas places it where antibodies can reach.
Gene: Protein-coding gene on chromosome 17 (39,671,122 to 39,696,797, reverse strand). Ensembl gene ENSG00000161395.
Subcellular location: Golgi apparatus membrane
Subcellular location (Human Protein Atlas): Cytosol; Plasma membrane
Gene Ontology:
Molecular function: hydrolase activity, acting on ester bonds; protein binding
Biological process: GPI anchor biosynthetic process; GPI anchored protein biosynthesis
Cellular component: cytoplasmic vesicle; Golgi membrane
Genetic constraint (gnomAD): Loss-of-function variants: 31 observed, 36.47 expected, observed/expected ratio (o/e) 0.85, 90% interval 0.64 to 1.15. The upper end of that interval is the gene's LOEUF score, 1.15, which puts it in group 5 of 6, group 1 being the genes least tolerant of losing a copy. Missense variants: 406 observed, 381.36 expected, observed/expected ratio (o/e) 1.06, 90% interval 0.98 to 1.16. Synonymous variants: 186 observed, 161.24 expected, observed/expected ratio (o/e) 1.15, 90% interval 1.02 to 1.3.
Gene-disease validity (ClinGen):
ClinGen rates the evidence that PGAP3 causes each of these diseases.
hyperphosphatasia with intellectual disability syndrome 4 (autosomal recessive): Definitive.
Homologues: Orthologues: chimpanzee PGAP3 (99% identical), macaque PGAP3 (99% identical), dog PGAP3 (92% identical), pig PGAP3 (90% identical), guinea pig PGAP3 (88% identical), rabbit PGAP3 (86% identical), mouse Pgap3 (85% identical), rat Pgap3 (84% identical), zebrafish pgap3 (65% identical), tropical clawed frog pgap3 (64% identical), Drosophila melanogaster PGAP3 (37% identical), Caenorhabditis elegans pgap-3 (28% identical).
Diseases named in the same sentence as PGAP3 in open-access papers:
PGAP3 is named in the same sentence as 46 diseases in open-access papers, as found by Europe PMC text mining. Sharing a sentence is not in itself a finding about the gene and the disease. The quoted sentences say what the papers report.
asthma (12 papers, 2011 to 2025). "Genetic association studies have linked PGAP3 SNPs to increased PGAP3 expression as well as asthma exacerbations, severity, and susceptibility." (PMID 40131902, 2025). "Several studies of PGAP3 have shown that the PGAP3 SNPs rs2517954, rs2517955, and rs2941504 increase asthma exacerbations, severity, and susceptibility." (PMID 40131902, 2025). "RNA-seq studies of ASM transfected with PGAP3 demonstrated significantly increased levels of genes linked to asthma including GATA3 and ALOX5." (PMID 40131902, 2025). "Among the protein-coding genes causally associated with unspecified asthma in lung and blood, seven are within the 17q12-21 locus (i.e., PGAP3, IKZF3, GSDMB, ORMDL3, GSDMA, MED24, and CASC3)." (PMID 39628479, 2024). "Given that rs2941504 resides within a PGAP3 intron, other variants in the gene may contribute to differing associations with asthma and LRTI by influencing alternative splicing and diversifying gene function." (PMID 40867500, 2025). "Moreover, RNA-seq studies demonstrated that increased PGAP3 expression in ASM increased levels of genes previously linked to asthma including GATA3 and ALOX5." (PMID 40131902, 2025). "Whether alternative splicing or GPI-Aps-driven immune signaling pathways underlie the divergent association of PGAP3 with asthma risk and RSV LRTI is a topic for future research." (PMID 40867500, 2025). "Thus, PGAP3 expression in NHBE regulates expression of genes known to be linked to asthma, and also regulates the bronchial epithelial expression of genes pertinent to the pathogenesis of respiratory viral triggered asthma exacerbations." (PMID 40131902, 2025). "For example, SNPs at STARD3/PGAP3 are strongly associated with the high atopic dermatitis subgroup suggesting that STARD3/PGAP3 may act on the allergic component of asthma." (PMID 29855310, 2018). "We have examined the effect of increased expression of PGAP3 in two cell types important to the pathogenesis of asthma, i.e., ASM cells in this study as well as in bronchial epithelial cells in a prior study." (PMID 40131902, 2025). "Post-GPI Attachment to Proteins phospholipase 3 (PGAP3) is a glycosylphosphatidylinositol (GPI) anchor-remodeling gene found on chromosome 17q12-21, which is a locus highly linked to asthma." (PMID 40131902, 2025). "We identified that PGAP3 upregulated 151 ASM-NA (SC) genes that were also detected in a GWAS asthma reference data set." (PMID 40131902, 2025). "For comparison, PGAP3 overexpression in NHBE identified 62 genes in a GWAS asthma reference data set." (PMID 40131902, 2025). "This suggests that PGAP3 overall upregulated many more genes in ASM than in airway epithelium of importance to asthma." (PMID 40131902, 2025). "We have previously reported that transfection of NHBE with PGAP3 upregulates genes and pathways of potential importance to asthma." (PMID 40131902, 2025). "We identified 15 genes that were upregulated by PGAP3 in ASM-NA (SC) that were also detected in one of the three asthma ASM reference data sets." (PMID 40131902, 2025). "The second most prominent asthma-related PGAP3-upregulated gene in ASM found in our data set is ALOX5 (FC = 4.88)." (PMID 40131902, 2025). "Fifteen genes upregulated by PGAP3 in ASM-NA were detected in asthmatic ASM data sets, underscoring the ability of PGAP3 to induce genes of importance to asthma in ASM." (PMID 40131902, 2025). "The most prominent asthma-related PGAP3-upregulated gene in ASM found in our data set is GATA3, which was the fourth highest expressed gene (FC = 4.99) induced by PGAP3 in ASM." (PMID 40131902, 2025). "Two of the highest expressed genes induced by PGAP3 in NHBE are RSAD2 and OASL, which are anti-viral genes associated with asthma." (PMID 40131902, 2025). "RNA-sequencing was used to determine if increased PGAP3 expression induced by plasmid PGAP3 transfection of ASM-NA (SC) cells influences the expression of genes that contribute to asthma." (PMID 40131902, 2025).
asthma (continued). "Overall, these studies suggest that increased PGAP3 expression in ASM plays a functional role in contributing to the pathogenesis of asthma." (PMID 40131902, 2025). "Since GPI-APs include cell adhesion molecules, enzymes, and receptors, an increase in PGAP3 expression related to asthma may impact their function." (PMID 40131902, 2025). "In addition, when ASM from non-asthmatics are transfected with PGAP3, the increased levels of PGAP3 increase ASM proliferation and contractility, and increase levels of genes previously linked to asthma including GATA3 and ALOX5." (PMID 40131902, 2025). "Moreover, genes related to growth and development (e.g., ERBB2, CDK2, PGAP3) were upregulated in asthma, which led to the feature of airway remodeling in the asthmatic monkeys." (PMID 36439114, 2022). "SNPs extending both proximal (including PGAP3 and ERBB2) and distal (including GSDMA) to the core region show less LD with those in the core region and have been implicated as potentially independent asthma risk loci." (PMID 34629083, 2021). "Thus, PGAP3 expression in epithelial cells could play a role in innate immune response to viruses (such as rhinovirus) which trigger asthma exacerbations." (PMID 40131902, 2025). "First, the association between allele rs2941504-A in PGAP3 (previously associated with asthma risk) and decreased risk of RSV LRTI led us to speculate the involvement of PGAP3 in distinct downstream mechanisms of asthma development and RSV LRTI risks." (PMID 40867500, 2025). "An overall comparison between the PGAP3 upregulated genes in ASM-NA (SC), PGAP3 upregulated genes in NHBE, and the GWAS asthma reference data set was performed to identify genes in common in all three datasets of relevance to asthma." (PMID 40131902, 2025). "Our Bioinformatic analysis of the 1,445 PGAP3 upregulated genes in the ASM dataset identified that approximately 10.5% of these genes (i.e., 151 genes) were found in a GWAS asthma reference data set." (PMID 40131902, 2025). "Two other notable genes upregulated by PGAP3 in ASM are BMP4 (FC = 3.12) and SERPINB5 (also known as Maspin, FC = 3.50), which each have studies supporting their potential role in asthma." (PMID 40131902, 2025). "Of these 151 PGAP3 upregulated genes found in both our ASM-NA (SC) data set and in the Asthma Reference data set, GATA3 had the highest overall fold change (FC = 4.99)." (PMID 40131902, 2025). "Overall, these studies suggest that increased PGAP3 expression in ASM plays an important functional role in ASM in contributing to airway hyperreactivity (AHR) and the pathogenesis of asthma." (PMID 40131902, 2025). "Given the importance of epithelial integrity in asthma, we assume that ORMDL3 and PGAP3 directly affect the function of renal epithelial cells." (PMID 37064151, 2023). "At present little is known about whether lung cells in asthma express PGAP3 at higher levels than non-asthmatics." (PMID 40131902, 2025). "In addition, when ASM from non-asthmatics are transfected with PGAP3, the increased levels of PGAP3 increased ASM proliferation and contractility, and increased levels of genes previously linked to asthma including GATA3 and ALOX5." (PMID 40131902, 2025). "As levels of PGAP3 in ASM from asthma are unknown, in this study we investigated whether levels of PGAP3 were increased in ASM from asthmatics as compared to non-asthmatics." (PMID 40131902, 2025). "Therefore, GSDMB, PGAP3, and ORMDL3 are the leading candidate asthma genes." (PMID 37064151, 2023). "We examined whether any of the PGAP3 upregulated genes we detected in ASM-NA (SC) could also be detected at increased levels in ASM from asthmatics using RNA-seq data sets from three prior studies of genes upregulated in asthma compared non-asthma control ASM." (PMID 40131902, 2025).
asthma (continued). "Some of the SNPs are in or close to the genes PGAP3 and STARD3 on chromosome 17, and interestingly, rs2941504 has been reported in a recent independent study to be associated with asthma, although it does not meet the criteria for inclusion in the GWAS catalog." (PMID 23755072, 2013). "In addition, this study demonstrated that when ASM from non-asthmatics were transfected with PGAP3, the increased levels of PGAP3 in ASM increased ASM proliferation and ASM contractility, which are cardinal features of ASM in asthma." (PMID 40131902, 2025). "Although the pathways that mediate PGAP3 induced ASM proliferation and contractility are not known, RNA-Sequencing of ASM expressing PGAP3 identified four genes significantly upregulated by PGAP3 that have known relevance with asthma (i.e., GATA3, ALOX5, BMP4, and SERPINB5)." (PMID 40131902, 2025).
breast carcinoma (9 papers, 2017 to 2024). "Specific amplification of the locus harbouring PGAP3 has been detected in breast carcinoma samples, and the identification of the CNV of PGAP3 is important for the accurate diagnosis of BC subtypes." (PMID 38378679, 2024). "This study has demonstrated strong predictive ability of GRB7 and PGAP3 in combination for detecting HER2 amplified breast cancers." (PMID 37809181, 2023). "Potential therapeutic inbreast cancer by regulating breast cancer-related genes,including SERPINE1, PGAP3, MAP3K1, MAPK1, GSTO2, VIM, SPARC, and FGF2." (PMID 37191432, 2023). "The consensus “HER2 amplicon” in breast cancers located at the 17q12–21 chromosomal region contains (besides ERBB2) at least five other genes (STARD3, TCAP, PNMT, PGAP3, and MIEN1)." (PMID 36139701, 2022).
hyperphosphatasia (8 papers, 2016 to 2024). "Some of the affected members were indeed found to harbor a deep intronic variant in the PGAP3, which was recently reported to cause hyperphosphatasia with mental retardation syndrome type 4 (OMIM 615,716)." (PMID 36344539, 2022). "Recessive mutations in Post-GPI attachment to proteins 3 (PGAP3) cause the rare neurological disorder hyperphosphatasia with mental retardation syndrome 4 type (HPMRS4)." (PMID 32726939, 2020). "Mutations in six different genes (PIGV, PIGY, PIGO, PGAP2, PIGW, and PGAP3) involved in GPI-anchor biosynthesis have been shown to cause hyperphosphatasia with mental retardation syndrome (HPMRS)." (PMID 29119105, 2017). "Recently, mutations have been identified in six genes (PIGA, PIGY, PIGO, PGAP2, PIGW and PGAP3) encoding proteins in the Glycosyl phosphatidylinositol(GPI)-anchor-synthesis pathway in individuals with hyperphosphatasia with impaired intellectual development syndrome(HPMRS)." (PMID 39687712, 2024). "To date, mutations in six genes (PIGV, PIGY, PIGO, PGAP2, PIGW, and PGAP3) have been shown to cause hyperphosphatasia with mental retardation syndrome (HPMRS) in an autosomal recessive mode of inheritance (no autosomal dominant mutations have been reported thus far)." (PMID 29119105, 2017).
gastric cancer (5 papers, 2010 to 2023). A primary or metastatic malignant neoplasm involving the stomach. "The locus at 17q12 erb‐b2 receptor tyrosine kinase 2 (ERBB2) has been heavily amplificated and overexpressed in gastric cancer (GC), but it remains to be elucidated about the clinical significance of the co‐amplification and co‐overexpression of PGAP3 gene located around ERBB2 in GC." (PMID 37386793, 2023).
Mabry syndrome (3 papers, 2015 to 2023). "Cleft palate as the only associated malformation found in this cohort has been previously documented in other individuals with HPMRS due to mutations in PGAP3 but also in the other groups of Mabry syndrome." (PMID 27120253, 2016). "In the current manuscript, we present eight previously unreported patients with Mabry syndrome carrying novel mutations in PGAP3, a gene of the GPI‐anchor maturation." (PMID 27120253, 2016). "Considering all molecularly confirmed cases of Mabry syndrome in our laboratory over the last 5 years, PGAP3 has now become the second most prevalent disease gene for this phenotypic series after PIGV." (PMID 27120253, 2016). "Hyperphosphatasia Mental Retardation syndrome (HPMRS, MIM 239300, MIM 214749, and MIM 614207), also known as Mabry syndrome, was found to be associated with PIGV (MIM 610274), PIGO (MIM 614730),PGAP2 (MIM 615187) and PGAP3 (MIM 611801) mutations." (PMID 25885527, 2015).
allergic rhinitis (2 papers, 2022 to 2023). Inflammation of the nasal mucous membranes caused by an IgE-mediated response to external allergens. "Similarly, the transcriptional regulation of LRP1 altered by rs1385526 in smooth muscle cells and PGAP3 altered by rs10558975 in enterocytes were considered to underlie hayfever/allergic rhinitis and inflammatory bowel disease (IMD), respectively." (PMID 37391400, 2023).
developmental delay (2 papers, 2016 to 2018). "All patients with genetic alterations in PGAP3 have a combination of severe global developmental delay and elevated levels of alkaline phosphatase activity, which are the most indicative features for HMPRS." (PMID 27120253, 2016). "Furthermore, the cell surface levels of CD55 and CD59 were on average lower in cells that were derived from individuals with mutations in PGAP3 compared to individuals with mutations in PIGV, although this did not correspond to a higher prevalence of seizures or a more severe developmental delay." (PMID 29310717, 2018).
gastric tumors (2 papers, 2010 to 2023). "The co‐amplification and co‐overexpression of PGAP3 and ERBB2 implicated their potential role in gastric tumour pathogenesis." (PMID 37386793, 2023).
inflammatory bowel disease (2 papers, 2019 to 2023). A spectrum of small and large bowel inflammatory diseases of unknown etiology. "Inverse relation between PGAP3 and MIEN 1 proteins in Inflammatory bowel disease (IBD)." (PMID 31552186, 2019).
allergic disease (1 paper, 2017). An immune response that occurs following re-exposure to an innocuous antigen, and that requires the presence of existing antibodies against that antigen. "Some of these genes have a known function that is relevant to allergic disease, including F11R, CD247, PGAP3, AAGAB, CAMK4 and PEX14, and so could be prioritized for functional follow-up." (PMID 29333270, 2017).
atopic asthma (1 paper, 2025). An asthma that is characterized by symptoms that are triggered by an allergic reaction caused by inhaled allergens such as dust mite allergen, pet dander, pollen and mold. "Conversely, the inverse association between rs2941504 in PGAP3 and RSV LRTI severity suggests that pathways involving GPI-APs regulated by PGAP3 gene region and known to skew immune responses toward a T2 profile characteristic of atopic asthma may confer protection from severe viral infections." (PMID 40867500, 2025).
bladder cancer (1 paper, 2017). "Genes co-amplified with ERBB2 (GRB7, MIEN1, PGAP3, and STARD3) exhibited the highest amplification frequency in esophageal cancer, followed by stomach, breast, uterine, and bladder cancer." (PMID 29190909, 2017).
epilepsy (1 paper, 2025). A brain disorder characterized by episodes of abnormally increased neuronal discharge resulting in transient episodes of sensory or motor neurological dysfunction, or psychic dysfunction. "Pathogenic variants in genes, such as PGAP3, CHD3, and SMAD6, can impair motor and cognitive performance without producing major neurological symptoms like epilepsy, suggesting that these deficits arise from developmental or structural abnormalities rather than from direct neurodegeneration." (PMID 41300846, 2025).
gout (1 paper, 2024). A condition characterized by painful swelling of the joints, which is caused by deposition of urate crystals. "Elevated expression of KRTCAP2 and PGAP3 is linked to an increased risk of gout, whereas higher expression of THBS3, THBS3-AS1, and KAT5 is associated with a reduced risk of the disease." (PMID 39161423, 2024). "Notably, increased expression of KRTCAP2 and PGAP3 is associated with an increased risk of gout, whereas increased expression of THBS3, THBS3-AS1, and KAT5 is associated with a reduced gout risk." (PMID 39161423, 2024).
Hereditary breast cancer (1 paper, 2019). Breast carcinoma that has developed in relatives of patients with history of breast carcinoma. "Among the highest-scoring genes detected using the proposed method, it is suspected that STARD3, PGAP3, ORMDL3, PSMD3 and HAPLN3 are the biomarkers of the HER2 + subtype, thus indicating that FOXC1 can identify basal-like subtypes in hereditary breast cancer cohorts." (PMID 31296201, 2019).
hypophosphatasia (1 paper, 2024). Hypophosphatasia (HPP) is a rare heritable metabolic disorder characterized by defective mineralization of bone and/or teeth in the presence of reduced activity of unfractionated serum alkaline phosphatase (ALP). "A lack of a GPI anchor on PGAP3 causes disorders such as hypophosphatasia." (PMID 39883197, 2024).
intestinal tumour (1 paper, 2023). "Moreover, we also found that co‐overexpression of the PGAP3 and ERBB2 was correlated with T stage, TNM stage, tumour size and intestinal tumour phenotype in GC." (PMID 37386793, 2023).